TLR9 (toll like receptor 9)
Diseases named in the same sentence as TLR9 in open-access papers (continued):
Sharing a sentence is not in itself a finding about the gene and the disease.
triple-negative breast carcinoma (14 papers, 2013 to 2024). An invasive breast carcinoma which is negative for expression of estrogen receptor (ER), progesterone receptor (PR), and human epidermal growth factor receptor 2 (HER2). "Low TLR9 expression is associated with poor prognosis specifically in triple negative breast cancer (TNBC)." (PMID 39644451, 2024). "Low tumor TLR9 expression has been associated with poor survival in Caucasian patients with triple negative breast cancer (TNBC)." (PMID 28886076, 2017). "In contrast, low expression of TLR9 is reported to be associated with a poorer prognosis in patients with triple-negative breast cancer." (PMID 29225688, 2017). "We previously demonstrated that low tumor TLR9 expression upon diagnosis is associated with significantly shortened disease-specific survival times in patients with triple-negative breast cancer (TNBC)." (PMID 24273604, 2013). "Our previous findings suggest that a moderate expression of TLR9 can be considered a prognostic factor in triple-negative breast cancer." (PMID 34479492, 2021). "Based on these trials in lung, the finding that high TLR9 expression in triple negative breast cancer is predictive of an improved prognosis is another area of interest therapeutically." (PMID 29190881, 2017). "We studied the prognostic significance of tumor Toll like receptor-9 (TLR9) protein expression among African American (AA) triple negative breast cancer (TNBC) patients." (PMID 28886076, 2017). "In the studies conducted so far, tumor TLR9 expression has been shown to have prognostic significance only in patients that have triple-negative breast cancer (TNBC)." (PMID 25101078, 2014). "Furthermore, TLR9 overexpression in triple-negative breast cancer leads to epithelial-to-mesenchymal transition (EMT) induction and EGFR pathway deregulation, suggesting a role in the carcinogenesis of this tumor subtype." (PMID 34573939, 2021). "Furthermore, the upregulation of TLR9 has been linked to specific breast cancer subtypes, particularly estrogen-receptor-negative (ER-) and triple-negative breast cancers (TNBC), which are known to exhibit a poorer prognosis and limited treatment options compared to hormone-receptor-positive tumors." (PMID 39123407, 2024). "For example, downregulation of TLR5 in triple-negative breast cancer (TNBC) increased tumor invasiveness and epithelial–mesenchymal transition (EMT) expression and promoted TNBC metastasis; TLR9 agonist CpG oligonucleotide was widely shown to have an anti-tumor effect by stimulating local immunity." (PMID 36344505, 2022). "CQ had a promising effect on tumour growth and invasiveness, independent of the TLR9 status in triple-negative breast cancer cells in vitro, but it did not reduce the growth of orthotopic triple-negative breast cancer tumours in vivo." (PMID 29225688, 2017). "While MΦ were not included in Mella’s study, their research suggested that tumorigenic TLR9 and tumor-infiltrating CD8+ T-cells do not correlate with triple-negative breast cancer (TNBC) patient cohort." (PMID 34479492, 2021).
Insulin resistance (13 papers, 2016 to 2025). Increased resistance towards insulin, that is, diminished effectiveness of insulin in reducing blood glucose levels. "In contrast, restoration of TLR9 only in BM aggravated insulin resistance in HFD-fed TLR9 deficient mice." (PMID 36176986, 2022). "TLR9-deficient mice had less insulin resistance than wild-type mice on a choline-deficient amino acid-defined diet." (PMID 32714475, 2020). "Both TLR4- and TLR9-deficient mice are protected from high-fat diet-induced inflammation and insulin resistance, while mice deficient in TLR5 develop all features of metabolic syndrome including hyperphagia, obesity, insulin resistance, pancreatic inflammation, and hepatic steatosis." (PMID 27247565, 2016). "Beyond its implications in cancer, TLR9 is significant in adipose tissue biology, insulin resistance, and oxidative stress." (PMID 39123407, 2024). "In that study, the authors demonstrated the protective role of TLR9 in the development of insulin resistance by showing the exacerbation of insulin resistance and pro-inflammatory activation of macrophages in TLR9 deficient mice." (PMID 36176986, 2022). "They identified IFNα as a possible agent of hepatic insulin resistance and noted the number of IFNα-positive pDCs was consistently decreased in TLR9 KO mice fed a HFD compared with wild type mice fed a HFD." (PMID 33584545, 2020). "Another study, however, showed that TLR9 deficiency promoted insulin resistance in response to a HFD, suggesting anti-inflammatory roles of TLR9 in macrophage activation." (PMID 32714475, 2020). "Administration of a TLR9 inhibitory oligonucleotide to fat-fed WT mice reduced the accumulation of macrophages in adipose tissue and improved insulin resistance." (PMID 31582899, 2019). "Administration of a TLR9 inhibitory oligonucleotide at approximately 5 mg/kg, three times a week, resulted in reduced accumulation of macrophages in adipose tissue and improved insulin resistance." (PMID 33584545, 2020). "On the other hand, administration of an inhibitory oligonucleotide for TLR9, iODN2088, to HFD-fed wild-type mice attenuated inflammation in adipose tissue and improved insulin resistance." (PMID 32714475, 2020). "As blocking TLR9 signaling in diseased mice could reverse NASH by improving steatohepatitis, fibrosis, and insulin resistance, it serves as a promising target for therapeutic intervention." (PMID 39158380, 2025). "This could result in more attention being directed toward the role of TLR9 and STING signaling in the development of metabolic diseases, such as insulin resistance and hepatic diseases and advances being made in new therapeutic strategies." (PMID 36176986, 2022). "Furthermore, bone marrow-specific expression of TLR9 worsened insulin resistance under HFD feeding compared with that in mice lacking TLR9 in their body." (PMID 32714475, 2020).
nephritis (13 papers, 2012 to 2024). Inflammation of renal tissue. "TLR1 and TLR9 expression levels are increased in apoferritin-induced nephritis, and TLR9 polymorphisms are related to many human diseases, including IgA nephropathy." (PMID 24810370, 2014). "Pristane has been shown to induce aberrant expression of pathogen recognition receptors, namely, toll-like receptors (TLRs) including TLR4 and TLR9, in the kidney, and these TLRs are necessary for the development of pristane-induced nephritis." (PMID 32265909, 2020). "TLR7 was significantly upregulated in mice with moderate and severe nephritis, and TLR9 was significantly upregulated in moderate nephritis." (PMID 29190833, 2017). "One study showed that absence of TLR9 in B cells caused exacerbated nephritis, while overexpression of TLR9 in B cells caused reduction of both nephritis and proteinuria." (PMID 38791389, 2024). "looked into the relationship between BAFF/APRIL and TLR9 activation and discovered that APRIL is important in TLR9-induced nephritis-induced IgA overproduction and IgG-IgA IC formation." (PMID 37342346, 2023). "TLR9 inhibition even neutralized the beneficial effects of the TLR7 blockade on systemic autoantibody levels without affecting the effects of the TLR7 blockade on nephritis." (PMID 29650017, 2018).
type 1 diabetes (13 papers, 2014 to 2025). "Intriguingly, deficiency of TLR9 was found to enhance glucose tolerance, and improve insulin sensitivity of type 1 diabetes." (PMID 35707851, 2022). "Pattern recognition receptors (PRRs), such as Nod2, Nlrp3, Tlr2, Trl4, and Tlr9, are directly involved in type 1 diabetes (T1D) susceptibility." (PMID 32295112, 2020). "We, and others, have independently shown that TLR9-deficient (Tlr9−/−) NOD mice are protected from type 1 diabetes development." (PMID 30094467, 2018). "Although TLR9 has been demonstrated to be associated with SLE and type 1 diabetes, there are limited data regarding the levels of TLR9 in AITD patients." (PMID 28018345, 2016). "Statistically significant relationships were also found between the percentage (R = −0.67; p < 0.05) and the number (R = −0.53, p < 0.05) of CD19+ TLR9+ B cells and the level of fructosamine in a group of patients with newly diagnosed type 1 diabetes." (PMID 34830017, 2021). "It was found that the percentage of CD8+ TLR9+ T cells in children with type 1 diabetes less than 3 months was lower compared to the control group (p = 0.040)." (PMID 34830017, 2021). "The performed analysis showed a negative correlation of the percentage (R = −0.78; p < 0.05) and the number (R = −0.69, p < 0.05) of CD19+ TLR9+ B cells with the level of glycated hemoglobin in a group of patients with newly diagnosed type 1 diabetes." (PMID 34830017, 2021). "We aimed to fill the knowledge gap by investigating the role of TLR9 in the development and function of islet beta cells in type 1 diabetes, using NOD mice." (PMID 30094467, 2018). "Considering that islet beta cells undergo significant growth and remodelling, early in life, it is likely that TLR9 plays an important role in the development of type 1 diabetes, beyond any direct immune function." (PMID 30094467, 2018). "We generated Tlr9−/− NOD mice and examined them for type 1 diabetes development and beta cell function, including insulin secretion and glucose tolerance." (PMID 30094467, 2018). "Inhibition of TLR9 has not been explored in human type 1 diabetes; however, pre-clinical tests for identifying an effective and safe dose, route and timing of any potential agent would need to be conducted first." (PMID 30094467, 2018).
chronic lymphocytic leukemia (12 papers, 2013 to 2024). "In chronic lymphocytic leukemia cells, TLR9 activation can lead to the increased IκBz expression and IgM release." (PMID 31708740, 2019). "Reduced IFNα secretion after TLR9 stimulation was shown to be a feature of pDC in a mouse model of chronic lymphocytic leukemia (CLL), as well as in human CLL patients." (PMID 28536351, 2017). "TLR9 is expressed on chronic lymphocytic leukemia cells and will undergo apoptosis when given CpG ODN 2006 (TLR9 agonist) in vitro." (PMID 26379664, 2015). "Additionally, the TLR9 gene is significantly expressed in chronic lymphocytic leukemia cells." (PMID 36071076, 2022). "In this study, we aim to unravel the intricate involvement of TLR2, TLR4, TLR3, TLR7, TLR8, and TLR9 in the immunopathogenesis of common variable immunodeficiency—CVID (as PID)—and chronic lymphocytic leukemia—CLL (as SID)." (PMID 37626865, 2023). "Indeed, an increased expression of both CD86 and CD80 in response to TLR9 stimulation was shown in chronic lymphocytic leukemia, but not in response to TLR7 stimulations." (PMID 29805758, 2018). "Another group demonstrated that TLR9 signaling by CpG-B ODNs leads to NF-kB-dependent production of autocrine IL-10, which then activates JAK/STAT pathway-dependent tyrosine phosphorylation of STAT1 proteins and thereby engenders an apoptotic pathway in human chronic lymphocytic leukemia B-cells." (PMID 23561041, 2013).
colorectal cancer (12 papers, 2015 to 2026). A primary or metastatic malignant neoplasm that affects the colon or rectum. "The aim of this study was to investigate TLR2 (-196 to-174del), TLR4 (Asp299Gly and Thr399Ile) and TLR9 (T1237C and T1486C) gene polymorphisms at risk of colorectal cancer (CRC) development and progression." (PMID 29883450, 2018). "Similarly, the TLR9 agonist IMO has demonstrated the ability to synergize with cetuximab in KRAS mutant colorectal cancer models, highlighting the interconnectedness of these pathways." (PMID 41550766, 2026). "Furthermore, in an ischemia and reperfusion murine model, surgical stress caused NET formation that in turn promoted the development of liver metastases of colorectal cancer cells through the binding of NET-derived HMGB1 to TLR9 and activation of MAP kinases pathway." (PMID 41142788, 2025). "Furthermore, in colorectal cancer cells, NET-derived HMGB1 was shown to interact with TLR9 with the subsequent activation of MAP kinase pathway." (PMID 41142788, 2025). "We hypothesize that combining CD47 blockade with therapies that further reduce myeloid immunosuppression, a key mediator of immunotherapy resistance in MSS colorectal cancer, such as KRAS inhibitor, STING agonist, TLR9 agonist, GM-CSF, or inflammasome modulation, could be effective." (PMID 41171165, 2025).
glomerulonephritis (12 papers, 2012 to 2025). A renal disorder characterized by damage in the glomeruli. "Finally, a deficiency of A20 leads to an hyperactivation of B cells after BCR, LPS or CD40 activation and to the spontaneous production of autoantibodies but, similar to Carabin deficiency, an A20 defect is associated with the development of glomerulonephritis after TLR9 stimulation." (PMID 23109291, 2012). "Compared with Tlr7+/+ Tlr9–/– mice, Tlr779/779 Tlr9–/– mice demonstrated a dramatic amelioration of lupus disease, as evidenced by reduced splenomegaly, glomerulonephritis (GN) and interstitial nephritis (IN) scores." (PMID 40794441, 2025). "Critically, histologic analysis revealed drastically reduced glomerulonephritis and interstitial nephritis in B-Tlr7ΔTLR9–/– mice compared with Tlr9–/– controls." (PMID 37606042, 2023). "This study investigates dendritic cell TLR9 ligation in murine experimental anti-MPO glomerulonephritis." (PMID 36674855, 2023). "Tlr9-/- MRL/+ mice had notable glomerulonephritis at 30 weeks of age, a time point at which the majority of Tlr9+/+ MRL/+ mice had not yet developed any significant renal disease." (PMID 28278279, 2017). "CpG-DNA/TLR9-mediated glomerulonephritis as well as the transition from inflammation to fibrosis may be inhibited by targeted inhibition of TGF-β1 and PDGF-B through antibody therapy." (PMID 28356164, 2017). "Moreover, expression of TLR9, protein and mRNA, was observed in mice with glomerulonephritis correlating with proteinuria and interstitial inflammatory infiltrate." (PMID 27635115, 2016). "Our studies focus on proving that the TLR9/TGF-β1/PDGF-B pathway found in mice also exists in humans; we provide new evidence that TLR9 signals to induce TGF-β1 and PDGF-B, which are critical mediators of glomerulonephritis." (PMID 28356164, 2017). "Further studies are necessary to identify TLR9, TGF-β1, and PDGF-B as new therapeutic targets to prevent the development of glomerulonephritis and LN." (PMID 28356164, 2017). "However, compared with Tlr9+/–Tlr7–/– MRL/lpr mice, Tlr997Tlr7–/– mice had markedly exacerbated lupus disease, with increased spleen weight and higher glomerulonephritis and interstitial nephritis scores." (PMID 40794441, 2025). "B6.Plcg2Ali5/Ali5 bearing a gain of function mutation in phospholipase c gamma 2 had decreased anti-nucleosome autoantibodies and more frequent nucleolar ANA patterns with more severe glomerulonephritis when Tlr9 was absent." (PMID 28278279, 2017). "B6.MRL-Faslpr mice lacking Tlr9 had more severe splenomegaly, proteinuria and glomerulonephritis and displayed a shift in autoantibody profiles from homogenous to nucleolar HEp-2 antinuclear antibody (ANA) staining." (PMID 28278279, 2017).
inflammatory bowel disease (12 papers, 2013 to 2025). A spectrum of small and large bowel inflammatory diseases of unknown etiology. "Recent studies have proven that TLR9 has a key role in several pathologies such as gastrointestinal cancer and inflammation, especially in inflammatory bowel diseases (IBD)." (PMID 35670957, 2022). "T. halophilus strain KK221 strain induces INF-β through TLR3 and TLR9 on dendritic cells and contributes to the anti-inflammatory function against inflammatory bowel diseases." (PMID 30586377, 2018). "Weak TLR9 agonists, such as BL-7040, can upregulate miRNAs targeting BChE, offering a novel strategy to modulate inflammation in chronic inflammatory diseases like inflammatory bowel disease (IBD)." (PMID 40612057, 2025). "Indeed, human IECs constitutively express TLR3, TLR5, TLR9, NOD1, NOD2 and low levels of TLR2 and TLR4, where TLR4 is increased in inflammatory bowel disease (IBD) IECSs and intestinal macrophages." (PMID 36296363, 2022).
myocarditis (12 papers, 2014 to 2024). Myocarditis is a condition that is characterized by inflammation of the heart muscle (myocardium). "Further, the role of mitophagy and its function to remove mitochondrial material has to be discussed, since inhibition of mitophagy molecules caused TLR9-mediated inflammatory responses in cardiomyocytes, myocarditis and dilated cardiomyopathy." (PMID 35223833, 2022). "While TLR3- and TLR7-deficient mice developed similar levels of myocardial inflammation compared to the wild-type controls, TLR9-deficient mice exhibited more severe myocarditis." (PMID 34072044, 2021). "Mice deficient in TLR4 or TLR9 show attenuated myocarditis phenotypes accompanied by reduced production of inflammatory cytokines." (PMID 34504807, 2021). "In fact, it was recently reported that mtDNA induces Toll-like receptor 9-mediated inflammatory responses in cardiomyocytes leading to myocarditis." (PMID 38167524, 2024). "Mitochondrial DNA, if not be eliminated appropriately and timely by autophagy, can trigger IL-1β mediated myocarditis and dilated cardiomyopathy via TLR9 activation." (PMID 35379787, 2022). "During acute CVB3-induced myocarditis most of the plasma membrane and intracellular localized TLRs showed an enhanced gene expression, however, Tlr2, Tlr3, Tlr6, Tlr7, and Tlr9 displayed by far the highest increase of mRNA expression during acute disease." (PMID 29538462, 2018). "It was shown that mitochondrial DNA that escapes from autophagy cell-autonomously leads to Toll-like receptor 9-mediated inflammatory responses in cardiomyocytes and is capable of inducing myocarditis and dilated cardiomyopathy." (PMID 25409294, 2014). "Interestingly, merely the intracellular localized TLRs Tlr3, Tlr8, and Tlr9 demonstrated elevated gene expression also at the chronic stage of myocarditis (28 days pi CVB3)." (PMID 29538462, 2018). "Although TLR9 can recognize various DNA viruses unlike the indirect way of recognizing RNA viruses, TLR9-MyD88 signaling pathway mediates myocardial injury in acute phase rather than chronic phase CVB3-induced myocarditis." (PMID 35514979, 2022).
non-alcoholic steatohepatitis (12 papers, 2016 to 2025). "IR-SNAs comprised of (Au-SNA or L-SNA) and TLR9 antagonist oligonucleotides (4084 F) and displayed 8-fold increases in potency and 30% more diminution in fibrosis score in nonalcoholic steatohepatitis (NASH) bearing mice." (PMID 38951806, 2024). "High levels of mtDNA with the capacity to activate TLR9 have been found in plasma of patients and mice with nonalcoholic steatohepatitis (NASH), driving the inflammatory phenotypes peculiar to this widespread liver disease." (PMID 34831121, 2021). "For example, the plasma from mice and patients with nonalcoholic steatohepatitis (NASH) contains high levels of mtDNA that has the ability to activate TLR9." (PMID 33239048, 2020). "High levels of mitochondrial DNA (mtDNA) have been found in the plasma of patients and mice with non-alcoholic steatohepatitis (NASH), and these mtDNA fragments have the ability to activate Toll-like receptor 9 (TLR9), leading to the inflammation phenotype characteristic liver disease." (PMID 41234914, 2025).